AGO2 (argonaute RISC catalytic component 2)
Diseases named in the same sentence as AGO2 in open-access papers (continued):
Sharing a sentence is not in itself a finding about the gene and the disease.
cancer (continued). "Cancer-cell exosomes can even produce miRNAs cell-independently, by performing the entire process of miRNAs maturation from precursor miRNAs (pre-miRNAs), via their own Dicer and AGO2." (PMID 31877735, 2019). "Higher Drosha and AGO2 expressions have been reported to correspond to shorter overall survival or to shorter recurrence-free and cancer-specific survival in Kaplan–Meier analysis although we only found Drosha to be significantly correlated with prolonged overall survival." (PMID 29857476, 2018). "Of the many RBPs that bind to the KRAS 3′ UTR, AGO2, HuR (or ELAVL1), IGF2BP1/2/3, PUM2, EWSR1, TAF15, FUS, and TIA1 have been previously implicated in cancer." (PMID 26930719, 2016). "Taken together, these studies suggest that the AGO2 may play crucial roles in the cancer development and progression." (PMID 26545861, 2015). "Interestingly, one report has demonstrated that whilst Ago2 binds tRFs in cancer cells, they cannot repress gene targets." (PMID 26703738, 2015). "The Dicer protein is a part of the RISC loading, small RNA processing complex, including its co-factor TRBP (TAR RNA binding protein), PACT, and Ago2, which could affect its stability depending on their respective expression in cancer cells." (PMID 19672267, 2009). "We further examined whether the distribution of Ago2 between the fractions of plasma membranes, which are enriched with CAV1, and other membrane organelles is associated with Ago2/CAV1 interaction in the cancer cells." (PMID 38649663, 2024). "Through Ago2/CAV1 interaction, Ago2 is recruited into a distinct region associated with plasma membranes or caveolae, which results in an increase in specific miRNAs and, in turn, increases miRNA-mediated translational suppression in distinct regions of cancer cells." (PMID 38649663, 2024). "Moreover, Ago2 is dysregulated under many pathological conditions, such as cancer." (PMID 34596044, 2021). "In addition, circAGO2 facilitated its enrichment and activation on the 3’-untranslated region of target genes by interacting with human antigen R (HuR) protein, reducing argonaute 2 (AGO2) binding and repressing the silencing of AGO2/miRNA-mediated genes related to cancer progression." (PMID 32213977, 2020). "Thus, the contribution of TRIM71 to miRNA-mediated silencing as well as the functional relationship between TRIM71 and AGO2 with regard to the control of stem cell fate and cancer cell proliferation remain unclear." (PMID 31732746, 2019). "On the other hand, protein kinase A signaling has been shown to promote mammary tumorigenesis and to determine ERα repositioning at promoters and tamoxifen resistance; its inhibition by ERβ–AGO2 cooperation may thus negatively affect cancer cell proliferation and survival." (PMID 29017520, 2017). "Hence, under the global hypomethylation state during zygotic activity, intragenic L1 may be expressed which down-regulates these genes, perhaps by the same AGO2-dependent mechanism as described in cancer cells." (PMID 25409429, 2014). "Finally, we found that AGO2 targetsintronic L1 pre-mRNA complexes and represses cancer genes." (PMID 21423624, 2011). "Colocalization of Ago2 and CAV1 increases in A549 cancer cells and deletion of CBM of Ago2 decreases the colocalization of Ago2 and CAV1 in the cancer cells." (PMID 38649663, 2024). "Disruption of Ago2/CAV1 interaction by P2 peptides resulted in the disassociation of Ago2 and other RISC proteins, GW182 and Dicer, from the membranes of cancer cells." (PMID 38649663, 2024). "The prognostic correlation of AGO2 gene expression was strongest in ACC (HR: 7.07, P = 2.8e-06) compared to the 31 other TCGA cancer types studied." (PMID 39404265, 2024). "In this study, we identified the relationship between this unique Ago2/CAV1 interaction, Ago2 subcellular location, and cancer cell behavior." (PMID 38649663, 2024). "Blocking Ago2/CAV1 interaction with P2 peptides suppressed the expression of certain miRNAs, including miRNA-3613-3p, in the cancer cells." (PMID 38649663, 2024).
cancer (continued). "Blockage of Ago2/CAV1 interaction with Ago2 K212 substitution with alanine, which mimics K212 acetylation, reduced the invasion and tumorsphere formation of cancer cells." (PMID 38649663, 2024). "However, we observed that neither S387A substitution, dephosphorylation mimic, or S387E substitution, phosphorylation mimic, of Ago2, altered Ago2/CAV1 interaction (Fig. EV1H), supporting that Ago2/CAV1 interaction is not responsible for Ago2 association with endosomes in cancer cells." (PMID 38649663, 2024). "We show here that a positive charge of Ago2 K212, that is preserved by SIR2-mediated Ago2 deacetylation in cancer cells, is responsible for the direct interaction between Ago2 and Caveolin-1 (CAV1)." (PMID 38649663, 2024). "A549Ago2-KO/AID-Ago2Wt/Ago2∆ cancer cells were subcutaneously implanted into SCID mice, and the mice were injected with phosphate-buffered saline (PBS) or IAA for disruption of Ago2/CAV1 interaction." (PMID 38649663, 2024). "Ago2/CAV1 interaction acts as a secondary event in miRNA-mediated suppression and increases the complexity of miRNA actions in cancer." (PMID 38649663, 2024). "Membrane lysis with RIPA buffer was also required for the complete digestion of EV-associated Ago2 and CAV1 by protease K (Fig. EV5D), indicating the presence of both Ago2 and CAV1 proteins in the cancer cell-derived EVs." (PMID 38649663, 2024). "The results suggest that CBM of Ago2 is responsible for the increased colocalization of Ago2 and CAV1 in cancer cells." (PMID 38649663, 2024). "MicroRNA-3613-3p-mediated suppression of SCAI depends on the secondary event, Ago2/CAV1 interaction, and contributes to the aggressive phenotypes of cancer cells." (PMID 38649663, 2024). "The effects of Ago2/CAV1 interaction on a target gene involved in regulating cancer cell behavior, namely the suppression of cancer cell invasion (SCAI), were then examined." (PMID 38649663, 2024). "Thus, targeting AGO2 could eliminate senescent cancer cells." (PMID 36834846, 2023). "Our previous work identified a novel interaction between KRAS and AGO2 in both WT and mutant KRAS cell lines across multiple cell lineages and cancers via coimmunoprecipitation (Co-IP) followed by mass spectrometry (co-IP MS)." (PMID 35923912, 2022). "After assessing the endogenous regulators of the AGO2–RAS interaction, we next asked if AGO2 played a functional role in promoting mutant HRAS and NRAS cancers." (PMID 35923912, 2022). "In parallel to our studies with mutant KRAS, we set out to identify a role for AGO2 in mutant HRAS and NRAS-driven cancers." (PMID 35923912, 2022). "Both AGO2 and PTK2 are located on chromosome 8q24.3, which is among the most frequently amplified regions in human cancers." (PMID 35163650, 2022). "Despite the evidence for a functional role of mutant KRAS–AGO2 interaction in cellular transformation and proliferation, the role of AGO2 in mutant HRAS or NRAS cancers is unclear." (PMID 35923912, 2022). "Our prior work described an essential role for Argonaute 2 (AGO2), of the RNA-induced silencing complex, in mutant KRAS-driven cancers." (PMID 35923912, 2022). "Taken together, our study finds a novel role for AGO2 as a regulator of cellular proliferation and senescence in mutant HRAS and NRAS-driven cancers through an EGFR–AGO2–RAS signaling axis." (PMID 35923912, 2022). "It was shown that high levels of AGO2 protein enhanced neoplastic transformation driven by KRAS mutants, whereas knockout of AGO2 resulted in the growth arrest of KRAS-dependent cancer cells." (PMID 33668654, 2021). "CircAGO2 (hsa_circ_0135889), an intronic circRNA produced from the AGO2 gene, was upregulated in both GC and CRC and promoted the invasion, metastasis and cell growth of cancer in vitro and in vivo." (PMID 32213977, 2020). "Nudix Hydrolase 21 (NUDT21), an interacting partner of AGO2 and a key regulator of APA, is frequently downregulated in several cancers." (PMID 32276464, 2020).
cancer (continued). "Among analysis, MYC, Argonaute2 (AGO2), Y-box binding protein 1 (YBX1), cyclin E1 (CCNE1) were involved in organismal abnormalities and cancer." (PMID 27463019, 2016). "In this study, by taking a genome-wide approach, we found that human Ago1, but not Ago2, is pervasively associated with gene regulatory sequences known as promoter and interacts with the core component of the gene transcription machinery to exert positive impact on gene expression in cancer cells." (PMID 24086155, 2013). "When sorted tetraspanin+, Ago2+ and/or GW182+ populations of cMV were compared, miR expression was generally 5-fold higher in cancer patients than in healthy controls." (PMID 26082317, 2013). "Because Ago2/CAV1 interaction is present in cancer cells but not in normal cells, we assume that this interaction is associated with certain cancer cell-specific behaviors." (PMID 38649663, 2024). "We therefore set out to investigate whether Ago2/CAV1 interaction, as a secondary event, regulates miRNA-mediated mRNA suppression in cancer cells, using miRNA-3613-3p as an example." (PMID 38649663, 2024). "However, the nuclear localization of AGO2 is highly dynamic and in cancer cells, such as U2OS and HEK293, AGO2 localization is predominantly cytoplasmic, suggesting that the fluctuations of nuclear AGO2 are tightly regulated." (PMID 38994560, 2024). "Hence, Ago2/CAV1 interaction regulates the expression of certain miRNAs and is required for the miRNA-mediated mRNA repression in cancer cells (e.g., miR-3613-3p)." (PMID 38649663, 2024). "Among these inhibitors, TM attenuated Ago2/CAV1 interaction in both A549 and HCC1806 cancer cells." (PMID 38649663, 2024). "To examine whether blockage of Ago2/CAV1 interaction directly affects miRNA-mediated mRNA repression, we overexpressed miR-3613-3p mimics in A549 cancer cells." (PMID 38649663, 2024). "Because Ago2/CAV1 interaction is required, as a secondary event, in miRNA-mediated mRNA suppression (e.g., miR-3613-3p-mediated suppression of SCAI), this interaction increases the complexity of miRNA actions in cancer (blue arrows in right panel)." (PMID 38649663, 2024). "Although our previous work showed nuclear AGO2 localization in stem cells using immunofluorescence-based imaging, in cancer cells, the nuclear pool of AGO2 observed through biochemical fractionation is not reflected in the immunofluorescent imaging of AGO2." (PMID 38994560, 2024). "By contrast, the overexpressed miR-6126 mimics suppressed their target, GRP78 mRNA, in both P2- and P2S-treated A549 cancer cells, suggesting that miR-6126-mediated mRNA suppression does not depend on Ago2/CAV1 interaction." (PMID 38649663, 2024). "The upregulation of AGO2 and the subsequent promotion of FAK expression may represent a positive-feedback loop resulting in high FAK expression in cancers." (PMID 35163650, 2022). "Considering the sequence homology between RAS isoforms is 100% identical within the Switch II region, we asked whether the interaction between AGO2 and HRAS or NRAS could be detected endogenously in human cancer cell lines." (PMID 35923912, 2022). "AGO2’s RISC activity and miRNA duplex unwinding were inhibited by interaction with mutant KRAS, suggesting that the RAS–AGO2 interaction plays a dynamic role in promoting mutant KRAS-driven cancer." (PMID 35923912, 2022). "Furthermore, AGO2 related RIP assays showed that circ0101675, miR-1278 and WNT3A/5A were all enriched to AGO2 RNA binding protein in both H1299 and A549 cancer cells." (PMID 34093821, 2021). "Moreover, AGO2 protein seems to be involved in the negative regulation of FGF2, which is elevated in numerous cancers and contributes to rapid proliferation of cancer cells." (PMID 33668654, 2021). "Notably, we were able to experimentally demonstrate the circGPC3/miR-378a-3p/ASPM axis through luciferase assays, Ago2, RIP and circRNA pull-downs, as well as cancer phenotype assays." (PMID 34199580, 2021).
cancer (continued). "We identified a novel AGO2/miR-185-3p/NRP1 regulatory axis that modulates EMT and the metastatic capability of CRC cells, which might represent a regulatory process for cancer cell migration and metastasis in general." (PMID 33846300, 2021). "Moreover, we found that hypoxic stress significantly enhanced the recruitment of AGO2 to cytosolic MSI1 in GBM and PDAC cancer cells." (PMID 31903115, 2020). "AGO2-bound miRs are taken up by neuropilin-1 (NRP1) and the internalized miRs remain functional, as they specifically regulate proliferation and migration of cancer cells." (PMID 32276464, 2020). "It should be mentioned that mammalian Top3β-TDRD3 complex differs from its Drosophila counterpart in that it lacks stable association with AGO2, as evidenced by the absence of AGO2 in Top3β or TDRD3 immunoprecipitation from human cancer cell lines." (PMID 31683993, 2019). "As a component of RISC with Dicer and Ago2, TARBP2 might be degraded in cancer cells via selective autophagy." (PMID 30657254, 2019). "In summary, our results contribute to a better mechanistic understanding of the role of AGO2 in transcription regulation and may inform future avenues of research with respect to AGO1 and control of cancer progression." (PMID 30356106, 2018). "Deregulation of miRNAs in various cancers may be related with altered expression and function of the genes involved in the miRNA machinery components, including DGCR8 and AGO2." (PMID 23775303, 2014). "Collectively, the predominance of miRNAs in exosomes, rather than in Ago2 complexes, confirms that exosomes derived from RBCs are the principal transporters of these miRNAs, playing a crucial role in mediating intercellular communication to cancer cells." (PMID 41159542, 2026). "Argonaute RISC catalytic component 2 (AGO2), a core component of the RNA-induced silencing complex (RISC), facilitates the binding of miRNAs to their target mRNAs, leading to mRNA degradation or translational repression, a mechanism crucial for the regulation of gene expression in cancer." (PMID 40271197, 2025). "Blockage of Ago2/CAV1 interaction by the AID system has the same effects as P2 peptides on miRNA regulation and cancer cell behavior, suggesting that the altered miRNA regulation and cancer cell behavior by P2 peptides indeed result from the disruption of Ago2/CAV1 interaction." (PMID 38649663, 2024). "In addition, we also explored the expression of AGO2, EIF4E3, DCPS and EIF4E in pan-cancer." (PMID 37353728, 2023). "What’s more, the expression of some writer genes (METTL1 and WDR4) and reader genes (AGO2 and NCBP2) was significantly upregulated in most cancers, while the expression of some eraser genes (NUDT12 and NUDT16) and some reader genes (EIF4E3) were downregulated in most cancers." (PMID 36339001, 2022). "By large-scale data mining, we discovered that 1-nt-shorter miRNA isoforms were accumulated in cancer cells, which could not be loaded into AGO2 effectively." (PMID 39872754, 2022). "The microRNA (miRNA) expression levels are globally suppressed in human cancer compared to those in normal tissues, which are mostly contributed to genetic and epigenetic alterations in miRNA-processing machinery components such as DROSHA, DGCR8, XPO5, TARBP2, DICER, and AGO2 in human cancer." (PMID 30305728, 2019). "However, more regulator genes negatively related to those compounds, like AGO2, DCP2, EIF3D, EIF4E, LARP1, and NCBP3 (related to 30 cancer drugs both in GDSC and CTRP), indicating the patients with higher mRNA expression level of these regulator genes might sensitive to these compounds." (PMID 36092891, 2022).
cancer (continued). "Therefore, we propose that AGO2 protein conjugated SPIONs are a new class of theranostic nanoparticles and can be efficiently used as innovative, non-cationic, non-toxic gene therapy tools for targeted therapy of cancer." (PMID 32345308, 2020). "As miR-497-5p was not present in AGO2-RNP complexes in HepG2 and HuH7 cells and miR-195 and miR-125 had already been shown to bind to LINC00152 in other cancer entities, miR-143a-3p was selected for further analysis." (PMID 35563834, 2022).